SYT4 (synaptotagmin 4)
Description:
Synaptotagmin family member which does not bind Ca(2+) (By similarity). Involved in neuronal dense core vesicles (DCVs) mobility through its interaction with KIF1A. Upon increased neuronal activity, phosphorylation by MAPK8/JNK1 destabilizes the interaction with KIF1A and captures DCVs to synapses (By similarity). Plays a role in dendrite formation by melanocytes.
Synonyms: KIAA1342; HsT1192
Tractability: Antibody: UniProt predicts a signal peptide or a membrane-spanning region; its Gene Ontology location is reachable by antibodies, with medium confidence; the Human Protein Atlas places it where antibodies can reach. PROTAC: ubiquitination databases record sites on it.
Gene: Protein-coding gene on chromosome 18 (43,267,892 to 43,277,535, reverse strand). Ensembl gene ENSG00000132872.
Subcellular location: Cytoplasmic vesicle, secretory vesicle, neuronal dense core vesicle membrane
Subcellular location (Human Protein Atlas): Plasma membrane; Vesicles
Gene Ontology:
Molecular function: protein binding; calcium ion sensor activity; calcium-dependent phospholipid binding; SNARE binding; calcium ion binding
Biological process: negative regulation of catecholamine secretion; positive regulation of dendrite extension; calcium-dependent activation of synaptic vesicle fusion; dense core granule cytoskeletal transport; negative regulation of calcium ion-dependent exocytosis; positive regulation of calcium ion-dependent exocytosis; regulation of calcium ion-dependent exocytosis; vesicle fusion; vesicle-mediated transport; memory; negative regulation of protein secretion; negative regulation of retrograde trans-synaptic signaling by neuropeptide; negative regulation of secretion by cell; negative regulation of short-term neuronal synaptic plasticity; negative regulation of synaptic vesicle exocytosis; positive regulation of dense core granule exocytosis; positive regulation of glutamate secretion; regulation of dopamine secretion; regulation of endocytosis; regulation of postsynaptic dense core vesicle exocytosis; regulation of trans-synaptic signaling by BDNF, modulating synaptic transmission; regulation of vesicle fusion
Cellular component: axon; dense core granule membrane; exocytic vesicle; Golgi membrane; neuronal dense core vesicle; plasma membrane; synapse; synaptic vesicle membrane; astrocyte projection; dendrite; dense core granule; glutamatergic synapse; Golgi apparatus; membrane; microvesicle; neuron projection; neuronal cell body; neuronal dense core vesicle membrane; perinuclear region of cytoplasm; somatodendritic compartment; vesicle
Genetic constraint (gnomAD): Loss-of-function variants: 5 observed, 32.92 expected, observed/expected ratio (o/e) 0.15, 90% interval 0.078 to 0.32. The upper end of that interval is the gene's LOEUF score, 0.32, which puts it in group 1 of 6, group 1 being the genes least tolerant of losing a copy. Missense variants: 479 observed, 511.09 expected, observed/expected ratio (o/e) 0.94, 90% interval 0.87 to 1.01. Synonymous variants: 205 observed, 195.86 expected, observed/expected ratio (o/e) 1.05, 90% interval 0.93 to 1.17.
Homologues: Orthologues: chimpanzee SYT4 (100% identical), macaque SYT4 (99% identical), dog SYT4 (95% identical), rabbit SYT4 (95% identical), pig SYT4 (93% identical), guinea pig SYT4 (93% identical), mouse Syt4 (90% identical), rat Syt4 (90% identical), tropical clawed frog syt4 (82% identical), zebrafish syt4 (67% identical). Paralogues in human: SYT11 (52% identical), SYT7 (36% identical), SYT10 (32% identical), SYT6 (32% identical), SYT2 (31% identical), SYT1 (30% identical), SYT9 (30% identical), SYT3 (30% identical), SYT5 (29% identical), SYT17 (27% identical), DOC2B (24% identical), SYT12 (24% identical), and 19 more.
Diseases named in the same sentence as SYT4 in open-access papers:
SYT4 is named in the same sentence as 30 diseases in open-access papers, as found by Europe PMC text mining. Sharing a sentence is not in itself a finding about the gene and the disease. The quoted sentences say what the papers report.
Obesity (6 papers, 2015 to 2021). Accumulation of substantial excess body fat. "Increased vesicle binding of synaptotagmin-4 in oxytocin neurons is associated with obesity and mice overexpressing synaptotagmin-4 are obesogenic in contrast to mice deficient in synaptotagmin-4 that are resistant to diet-induced obesity." (PMID 34256847, 2021). "On the contrary, down-regulation of SYT4 normalized oxytocin release, indicating that obesity and its afflictions are under regulation of hypothalamic neuropeptides." (PMID 26337083, 2015). "In accordance with these observations, mice modified genetically to have a reduced PVN oxy signaling, such as single-minded 1 gene (SIM1) haploinsufficient mice or synaptotagmin 4 (SYT4) null mice, are characterized by a reduction in energy expenditure, hyperphagia and obesity." (PMID 26793046, 2015).
gastric cancer (3 papers, 2021 to 2025). A primary or metastatic malignant neoplasm involving the stomach. "Moreover, we uncovered a novel mechanism by which borussertib selectively inhibits SYT4's oncogenic activity, providing compelling evidence for its therapeutic potential in gastric cancer treatment." (PMID 41281742, 2025). "This study reveals SYT4’s overexpression in gastric cancer (GC) links to poor prognosis and aggressive traits, indicating its role in GC progression." (PMID 38632140, 2024). "By delving into the function of SYT4 and its molecular mechanisms in GC, particularly its interaction with Ca2+ signaling, this study could uncover new therapeutic strategies, providing more effective treatment options for patients with gastric cancer." (PMID 38632140, 2024). "To assess PSMC6's role in SYT4-driven gastric cancer progression, we co-transfected PSMC6 knockdown plasmids into SYT4-overexpressing (OE) cells." (PMID 41281742, 2025). "1.The expressions of SYT4, SYT9 and SYT14 were up-regulated in gastric cancer (GC)." (PMID 34229539, 2021).
Alzheimer disease (2 papers, 2013 to 2024). A progressive, neurodegenerative disease characterized by loss of function and death of nerve cells in several areas of the brain leading to loss of cognitive function such as memory and language. "Syt4 has been implicated in these diseases, and genome-wide association studies have found single nucleotide polymorphisms associated with Parkinson's disease and Alzheimer's disease; altered Syt4 expression has also been observed in an experimental model of ischemia." (PMID 39266302, 2024).
Anxiety (2 papers, 2011 to 2024). Intense feelings of nervousness, tension, or panic often arise in response to interpersonal stresses. "Future research could explore the potential relationship between Syt4 and oxytocin in the context of anxiety behaviors." (PMID 38297157, 2024). "We then investigated whether the inhibition of Syt4 expression (Syt4-KD) during CUS led to an improved pursuit of pleasure and/or reduced despair- and anxiety-like behaviors." (PMID 38297157, 2024).
depression (2 papers, 2011 to 2024). "Overall, our evidence indicated that the modulation of Syt4 expression in stressful settings was strongly associated with depression-like behaviors, including physical and social anhedonia." (PMID 38297157, 2024). "The sex-specific action of SYT4-BDNF in depression requires further investigation." (PMID 38297157, 2024). "The researchers concluded that SYT4 and BDNF play crucial roles in the development of anhedonia and stress-induced depression." (PMID 38297157, 2024). "However, further studies are needed to investigate the relationships among SYT4, BDNF, and sex hormones in female patients with depression to develop optimized precision interventions for treating depression, especially for females, who have a greater lifetime incidence of depression than males." (PMID 38297157, 2024).
epilepsy (2 papers, 2020 to 2025). A brain disorder characterized by episodes of abnormally increased neuronal discharge resulting in transient episodes of sensory or motor neurological dysfunction, or psychic dysfunction. "Moreover, among the genes within a short region of overlap of these deletions, the SYT4 gene (MIM 600103)—which encodes a highly conserved membrane protein involved in synaptic function—may play a role in proximal 18q deletion syndromes as a factor predisposing to epilepsy." (PMID 41300786, 2025).
lymph node metastasis (2 papers, 2024 to 2025). "High SYT4 levels were associated with several factors, including increased Ki-67 expression, lymph node metastasis, poor tissue differentiation, advanced T stage, perineural invasion, vascular invasion, TNM stage, and larger tumor size." (PMID 41281742, 2025). "Univariate analysis confirmed that age, tumor size, T stage, N stage, lymph node metastasis, vascular invasion, nerve invasion, TNM stage and SYT4 expression were significantly associated with poorer OS (all P < 0.001)." (PMID 38632140, 2024).
alcohol dependence (1 paper, 2005). Physical and psychological dependence on alcohol. "Based on the evidence from our linkage study and the gene function revealed by other studies, SYT4 may be a determinant of alcohol dependence and is a candidate for further study." (PMID 16451610, 2005).
diabetes neuropathies (1 paper, 2020). "The negative regulation of SYT4 could potentially repair or reduce the degree of diabetes neuropathies; however, the physiological function of SYT4 remains unknown." (PMID 32982666, 2020).
gastric adenocarcinoma (1 paper, 2022). "It is now known that SYT4 has a role in gastric adenocarcinoma and low-grade glioma and is associated with recurrence-free survival in BC." (PMID 36553681, 2022).
glioblastoma (1 paper, 2022). The most malignant astrocytic tumor (WHO grade IV). "Likewise, other bioinformatics analysis identified SYT4 (human orthologue of Syt 4) as a potential core gene for glioblastoma." (PMID 35877760, 2022).
malignant glioma (1 paper, 2025). A grade III or grade IV glioma arising from the central nervous system. "According to the literature, Syt4 is a prognostic marker of low-grade malignant glioma." (PMID 41009560, 2025).
melanoma (1 paper, 2025). A malignant, usually aggressive tumor composed of atypical, neoplastic melanocytes. "In alpaca melanocytes and melanoma cells, SYT4 overexpression regulates calcium influx through TRPM1 and promotes dendrite elongation." (PMID 40354322, 2025).
triple-negative breast carcinoma (1 paper, 2021). An invasive breast carcinoma which is negative for expression of estrogen receptor (ER), progesterone receptor (PR), and human epidermal growth factor receptor 2 (HER2). "SYT4 is up-regulated in triple-negative breast cancer, confers paclitaxel resistance, and leads to poor prognosis." (PMID 34229539, 2021).
cancer (6 papers, 2019 to 2025). A tumor composed of atypical neoplastic, often pleomorphic cells that invade other tissues. "Previous studies have implicated SYT4 involved in cancer progression via modulation of Ca2+ influx." (PMID 38632140, 2024). "GEO and The Cancer Genome Atlas-Stomach Adenocarcinoma (TCGA-STAD) datasets were scrutinized to evaluate SYT4 mRNA levels." (PMID 38632140, 2024). "According to increasing evidence on the correlations between immune cell infiltration and prognosis in cancer, we utilized the TIMER database to evaluate the association between the expressions of SYT4, SYT9, and SYT14 and immune cell infiltration." (PMID 34229539, 2021). "Moreover, SYT4 has been reported to play an oncogenic role in cancer progression through genetic alterations." (PMID 41281742, 2025). "Our findings indicate that borussertib, a selective inhibitor, could be developed into a targeted therapy to specifically disrupt the cancer-promoting actions of SYT4." (PMID 41281742, 2025).
tumor (5 papers, 2022 to 2025). "Approximately half of the tumor cells or less demonstrated high expression of Syt4, Ankd37, and Slc2a3." (PMID 41009560, 2025). "Collectively, these findings suggested that SYT4 silencing can effectively suppress the growth of GC cells in vivo, as evidenced by smaller tumor size and lower proliferative activity." (PMID 41281742, 2025). "The results demonstrated that the tumor size and weight in mice injected with SYT4-KD cells were markedly reduced compared to those in mice injected with control cells." (PMID 41281742, 2025). "Collectively, these findings indicated that SYT4 plays a critical role in regulating the Wnt/β-catenin signaling pathway in GC, potentially driving tumor progression through this mechanism." (PMID 41281742, 2025). "In a mouse model with subcutaneous xenografts, SYT4 knockdown also led to reduced tumor growth, consistent with our in vitro findings." (PMID 41281742, 2025). "Collectively, these findings suggest that SYT4 significantly promotes cell proliferation, hinders apoptosis in vivo, and contributes to tumor growth in a mouse model." (PMID 38632140, 2024). "Immunohistochemical staining of tumor sections showed decreased expression of SYT4, Ki-67, and increased Caspase-3 in the knockdown group compared to controls." (PMID 38632140, 2024). "Furthermore, we identified borussertib, a covalent allosteric inhibitor of SYT4, which selectively suppresses SYT4-driven tumor growth in GC cells and xenograft models by inhibiting the Wnt/β-catenin pathway." (PMID 41281742, 2025). "Oral administration of amlodipine substantially reduced tumor growth and volume compared to the DMSO-treated group in SYT4-OE group." (PMID 38632140, 2024).
infection (1 paper, 2021). The state of being infected such as from the introduction of a foreign agent such as serum, vaccine, antigenic substance or organism. "Of these, CD44, KDM1B, FKBP4, TEF, SYT4, SATB1 and PLCD1 are reported to be involved in the inflammatory reaction; for the remaining ten genes, there have been no reports concerning inflammation or infection." (PMID 34046191, 2021).
neurodegenerative disease (1 paper, 2023). A disorder of the central nervous system characterized by gradual and progressive loss of neural tissue and neurologic function. "Therefore, it is highly possible that the ARMS regulates BDNF secretion by modulating Syt4 levels, and may thus play a key role in the regulation of nociception and neurodegenerative diseases." (PMID 38069318, 2023). "In conclusion, our study establishes a biochemical basis for understanding the formation of the ARMS/Syt4 complex, which is important for gaining insight into the mechanisms of the regulation of BDNF secretion and neurodegenerative diseases." (PMID 38069318, 2023).
SYT4 also shares sentences with these, for which no sentence is quoted: Parkinson disease (2 papers); prostate carcinoma (2); adenocarcinoma (1); asthma (1); diabetes mellitus (1); glioma (1); hepatocellular carcinoma (1); hyperglycaemia (1); immune disease (1); insulinomas (1); ischemia (1); neuropathies (1).